TRPM8 (transient receptor potential cation channel subfamily M member 8)
Diseases named in the same sentence as TRPM8 in open-access papers (continued):
Sharing a sentence is not in itself a finding about the gene and the disease.
prostate carcinoma (continued). "However, BCTC (10 μM) inhibited the growth of this cell line to a similar extent after TRPM8 knockdown, indicating that the effect of BCTC on prostate cancer cell proliferation is not entirely due to TRPM8 inhibition." (PMID 23251635, 2012). "At first view, the fact that TRPM8 expression is not exclusive of prostate cancer cells might be regarded as a drawback for the design of therapies based on TRPM8 inhibition." (PMID 23251635, 2012). "Altogether, our results suggest that sM8 isoforms participate in resistance against pro-apoptotic signals in prostate cancer cells and consequently that targeting sM8 isoforms rather than the TRPM8 channel itself could be an appropriate and beneficial strategy against extracapsular prostate cancer." (PMID 27074561, 2016).
migraine (63 papers, 2011 to 2025). "Another example of selection on a latitudinal cline has previously been obtained with TRPM8, a gene implicated in tolerance to the cold and associated with migraine." (PMID 39515300, 2024). "All three groups revealed a TRPM8 gene variant associated with increased susceptibility to migraine." (PMID 36986537, 2023). "Associations between SLC17A8, TRPV1, TRPV4 and TRPM8 gene polymorphisms and anxiety and depression in migraine patients." (PMID 37303955, 2023). "Dysregulation of TRPM8 activity underlies several physiopathological conditions, including painful cold hypersensitivity in response to axonal damage, migraine, dry-eye disease, overactive bladder, and several forms of cancer." (PMID 37388453, 2023). "The present study showed that TRPV1 rs8065080, TRPV3 rs7217270, and TRPM8 rs17862920 were significantly associated with migraine or MO risk." (PMID 37303955, 2023). "The role of the TRP melastatin 8 (TRPM8) channel in migraine was investigated after genome-wide association study (GWAS) analyses on three different groups of individuals with migraine." (PMID 36986537, 2023). "In univariate analysis, TRPM8 rs7577262 and TRPM8 rs17862920 were associated with migraine [OR (95% CI): 0.68 (0.49–0.93), p = 0.016; 0.71 (0.52–0.97), p = 0.031, respectively]." (PMID 37303955, 2023). "Associations between SLC17A8, SHANK1, TRPV1, TRPV3 and TRPM8 gene polymorphisms and the risk of migraine by aura." (PMID 37303955, 2023). "Recently, a significant correlation has been found between the incidence of migraine and single nucleotide polymorphisms (SNPs) closely associated with the TRPM8 coding region." (PMID 36831105, 2023). "In migraine patients, the TRPM8 rs7577262 was associated with decreased anxiety risk in a dominant model (ORadj = 0.27, 95% CI = 0.10–0.76, p = 0.011)." (PMID 37303955, 2023). "There is an association between migraine incidence and single nucleotide polymorphisms located near the TRPM8 coding region, although this seems to be the case mainly for people of Northern European ancestry." (PMID 36614146, 2022). "In animal experiments, dural administration of icilin caused facial and hindpaw allodynia in rats, indicating that activation of TRPM8 caused migraine-like behaviors." (PMID 36614146, 2022). "TRPM8 has been identified in several genome-wide association studies (GWAS) as one of the migraine susceptibility genes." (PMID 36614146, 2022). "TRPM8 channels have been implicated in a broad range of pathologies, among them different pain types, including migraine, dry eye disease, inflammatory processes, and cancer." (PMID 35976012, 2022). "Variants of TRPM8 have been associated with migraines (GWAS) and its expression is being found (e.g., in trigeminal ganglion)." (PMID 35625007, 2022). "Different conditions such as neuropathic pain, cancer, overactive bladder syndrome, migraine, and chronic cough have been linked to the TRPM8 mode of action." (PMID 36295712, 2022). "Several SNPs in TRPV1, TRPV3, and TRPM8 were found to be associated with migraine susceptibility in meta-analyses of observational studies and GWAS." (PMID 33193064, 2020). "It is intriguing, although evolutionary fitting, that single-nucleotide variants causing reduced TRPM8 expression, which is associated with a higher risk for migraine, are more frequently found in populations that live in warmer geographic areas." (PMID 31948011, 2020). "Another member of the TRP receptor family implicated in the migraine pathophysiology is the TRPM8 that is a cold-sensitive channel activated also by natural and synthetic “cooling” agents, such as menthol and icilin." (PMID 31948011, 2020). "Several single nucleotide polymorphisms (SNPs) related to the TRPM8 gene are associated with either the risk or protection from migraines." (PMID 33240883, 2020). "Our study shows that the TRPM8 variant rs10166942 is associated with chronic migraine and allodynia in patients with migraine." (PMID 31842742, 2019).
migraine (continued). "Based on our findings, a longitudinal study is warranted to elucidate the association between the TRPM8 genetic variant rs10166942 and the evolution of migraine." (PMID 31842742, 2019). "The T allele in the TRPM8 variant rs10166942 is a risk allele for migraine, and our results further indicate that it is also a risk allele to allodynia in migraineurs." (PMID 31842742, 2019). "Based on these results, TRPM8 variants identified in migraine patients likely contribute to migraine pathology." (PMID 31336748, 2019). "Based on AEI analysis, we present haplotype data suggesting that decreased expression of TRPM8 is associated with a reduced risk for migraine." (PMID 31873179, 2019). "Multiple genome-wide association studies have identified non-coding single-nucleotide variants (SNVs) near (e.g., rs10166942[C]) or within (rs17862920[T]) the TRPM8 gene that encodes a cold thermosensor is associated with reduced migraine risk." (PMID 31873179, 2019). "In this study, we have assessed the extent to which reduced migraine risk alleles affect TRPM8 expression by evaluating allelic expression imbalance (AEI) at the transcript level using next generation sequencing." (PMID 31873179, 2019). "We assessed if reduced migraine risk alleles would influence TRPM8 expression by evaluating allelic expression imbalance (AEI) at the transcript level using next generation sequencing." (PMID 31873179, 2019). "In several meta-analysis and genome-wide association studies (GWAS) the TRPM8 locus has been related to susceptibility to migraine." (PMID 30155469, 2018). "For example, TRPM8 was strongly linked to migraine in a human genome-wide association study, while genome-wide studies have not revealed such a link between TRPA1 and migraine." (PMID 30388732, 2018). "Burgos-Vega and colleagues observed that application of icilin to the dura mater resulted in reduced paw and facial withdrawal thresholds in response to a mechanical stimulus, indicating that activation of TRPM8 caused migraine-like behaviors." (PMID 28358322, 2017). "Intriguingly, a gene variant of TRPM8 was discovered to have a positive correlation with migraine susceptibility in women." (PMID 27854251, 2016). "TRPM8 has been implicated in pain and migraine based on dorsal root- and trigeminal ganglion-enriched expression, upregulation in preclinical models of pain, knockout mouse studies, and human genetics." (PMID 25662185, 2015). "Recent genome-wide association studies (GWAS) involving migraine patients have demonstrated a strong association of TRPM8 with migraine." (PMID 25662185, 2015). "The migraine-associated TRPM8 single nucleotide polymorphism variant is 950 bp upstream of the transcription start site for TRPM8 mRNA." (PMID 26111800, 2015). "Genome-wide association studies have identified TRPM8 (transient receptor potential melastatin 8) as one of the susceptibility genes for common migraine." (PMID 26111800, 2015). "Model selection with the Akiake information criterion (AIC) penalty was less stringent, identifying selective associations according to migraine characteristics for all SNPs except rs7577262 (TRPM8)." (PMID 24852292, 2014). "Accordingly, TRPM8 was found to be a susceptibility loci for common migraine and has been the focus of neuropathic pain models." (PMID 23805179, 2013). "Further, the association at rs10166942 (TRPM8) for the first time implicates a gene in a pain related pathway in migraine." (PMID 22072275, 2012). "For example, the identification of KCNK18 and TRPM8 as migraine-associated genes, both highly expressed in sensory neurons, would certainly support the importance of peripheral neurons." (PMID 22027350, 2011). "Authors also mention mutations of specific ion channels, such as TRESK—potassium channels encoded by gene KCNK18, which regulates the dorsal roots and trigeminal ganglia excitability; TRPM8, and others, which are linked with inherited migraine, which emphasize ion channels’ role in migraine." (PMID 40227290, 2025).
migraine (continued). "Indeed, a prior bioinformatics report highlighted the role of TRPM8 as a potential biomarker for migraine susceptibility." (PMID 39857659, 2024). "Notably, TRPM8 has been implicated in neuropathic pain, migraines, and neurodegenerative diseases such as Parkinson’s disease." (PMID 39857659, 2024). "TRPM8 has consistently been linked to migraines in genetic studies." (PMID 39201645, 2024). "TRPM8 may be involved in the development of migraine as individuals with migraine protective alleles show reduced sensitivity to cold stimuli." (PMID 36831105, 2023). "We also found that TRPM8 rs7577262 was associated with migraine risk." (PMID 37303955, 2023). "Single nucleotide polymorphisms (SNPs) in TRPM8 have been associated with migraine; however, it is unclear whether some of these SNPs are beneficial or detrimental." (PMID 37175602, 2023). "In anxiety or depression patients, TRPM8 rs7577262 was still associated with migraine." (PMID 37303955, 2023). "TRPM8 rs7577262 was associated with migraine comorbidity anxiety." (PMID 37303955, 2023). "As the main members of the TRP family, the polymorphisms of TRPV1, TRPV4 and TRPM8 genes may play an important role in the occurrence and development of migraine." (PMID 37303955, 2023). "Associations between the GRIK2, TRPV1, TRPV3 and TRPM8 gene polymorphisms and the risk of migraine." (PMID 37303955, 2023). "Additionally, polymorphisms in the TRPM8 gene have been related to migraine by genome-wide association studies." (PMID 37388453, 2023). "Remarkably, there is also a possible role of TRPM8 in migraine as several large genome-wide association studies identified single nucleotide polymorphisms within and near the TRPM8 gene which confer a reduced risk of migraine." (PMID 35216232, 2022). "Moreover, some genome‐wide association studies have found some single‐nucleotide polymorphisms (SNPs) located in the TRPM8 gene that have been associated with migraine." (PMID 35976012, 2022). "It is currently unknown how these genetic variants affect the function or expression of TRPM8 and what is their role in migraine." (PMID 36614146, 2022). "Some experimental evidence indicated that TRPM8 channels are overexpressed in a rat model of migraine, and that these channels could be implicated in the migraine mechanism, possibly through activation of NMDA receptors." (PMID 35269831, 2022). "Moreover, we detected a significant association between the rs10166942 (near the TRPM8 gene) CT genotype and increased migraine risk and MO risk, while the homozygosities appear to confer a protective effect." (PMID 35454329, 2022). "In conclusion, based on our findings the PRDM16 rs2651899 is associated with migraine and MA, and the rs10166942 (near the TRPM8 gene) CT genotype is associated with increased migraine risk and MO risk, while the homozygosities appear to confer a protective effect." (PMID 35454329, 2022). "The transduction channel TRPM8 is interesting, because genome-wide association studies showed that it may be implicated in migraine." (PMID 32088764, 2020). "Although the exact mechanisms are unknown, a possible mechanism for TRPM8-mediated risk of migraine headaches might be related to this channel’s role in vasoconstriction regulation, which has been related to migraine development." (PMID 33240883, 2020). "This study provides evidence for a genotype-dependent influence on cold pain sensation suggesting that carriers of the reduced migraine risk allele have reduced sensitivity to cold stimuli and that TRPM8 acts as a cold thermosensor and cold pain transducer in humans." (PMID 31873179, 2019). "In addition, some studies strongly suggested a correlation between specific Single Nucleotide Polymorphisms SNPs in the TRPM8 encoding gene and migraine processes, thus positioning TRPM8 as a potential novel target for this disabling condition." (PMID 31141957, 2019).
migraine (continued). "Although TRPM8 variants are associated with migraine susceptibility, whether therapeutic strategies that target this channel should be agonists or antagonists, is unclear." (PMID 31336748, 2019). "The association between the TRPM8 variant rs10166942 and migraine was initially found in Western populations and replicated later in Asians; here, the T allele was the risk allele for migraine across all studies." (PMID 31842742, 2019). "TRPM8 expression is reduced from the chromosome harboring rs10166942[C] in all the carriers in the range of 47% to 99% with the maximum decrease observed from the chromosome that harbors both reduced risk migraine alleles (rs10166942[C] and rs17862920[T])." (PMID 31873179, 2019). "In addition to its role in somatic pain sensation, recent genome-wide association studies have found a significant correlation between migraine incidence and single nucleotide polymorphisms (SNPs) located near the TRPM8 coding region." (PMID 28358322, 2017). "TRPV1 rs222741 and TRPM8 rs7577262 may associate with migraine comorbidity anxiety risk." (PMID 37303955, 2023). "Furthermore, the association between migraine and rs10166942 in transient receptor potential melastatin 8 (TRPM8) as well as rs1172113 in low density lipoprotein receptor-related protein 1 (LRP1), the two most replicated SNPs in Caucasians, were also reproduced in our study cohort." (PMID 31842742, 2019). "Or, perhaps TRPM8 antagonists could still be useful therapeutics for any other cold-related painful allodynia or hyperalgesia associated with other neuropathic or inflammatory conditions or even migraine or bladder pain." (PMID 28358322, 2017). "Single nucleotide polymorphs (SNPs) within the TRPM8 gene have consistently been found to show a protective association with migraine in multiple studies as well as in a meta-analysis of all migraine GWAS suggesting that TRPM8 modulators may act as migraine therapeutics." (PMID 25662185, 2015). "A recent study showed that TRMP8 is expressed in the meninges, and neuroinflammatory events in the meninges lead to migraine‐like pain via glial cell‐derived neurotrophic factor family receptor alpha‐3 (GFRα3)‐TRPM8 signal pathway." (PMID 41399206, 2025). "Trpm8 deletion or ablation of TRPM8‐expressed neurons abolishes nitroglycerin‐induced migraine‐like pain in mice, and the selective TRPM8 antagonist 1‐phenylethyl‐4‐(benzyloxy)‐3‐methoxybenzyl (2‐aminoethyl) carbamate (PBMC) also shows similar effects." (PMID 41399206, 2025). "Other TRP channels, such as TRPV4, TRPM3, TRPC4 and TRPM8, remain reliable candidates to be involved in migraine pain signaling with potential to be drug targets." (PMID 38221631, 2024). "Among the TRP channels, TRPV1, TRPA1, and TRPM8 have been well studied and are being investigated as potential therapeutic targets for migraine prevention and treatment." (PMID 37175602, 2023). "TRPV4 rs3742037, TRPM8 rs17862920, TRPM8 rs10466942 and SLC17A8 rs11110359 were associated with migraine comorbidity depression risk." (PMID 37303955, 2023). "TRPA1, along with transient receptor potential cation channel subfamily V member 1 (TRPV1), TRPV4, and transient receptor potential cation channel subfamily M member 8 (TRPM8), are most consistently reported to associate with migraine among all TRP channels." (PMID 37326902, 2023). "A recent study using transgenic knockout TRPM8 mice suggests a protective role in promoting a faster recovery from chronic migraine-like symptoms in male mice compared to that in female mice." (PMID 37175602, 2023). "The TRPM8 has been shown to play a major physiological role in inflammation, thermoregulation, itch, and migraine." (PMID 36614146, 2022). "Our findings suggest a protective function of TRPM8 in shortening the time frame of hypersensitivity in a mouse model of migraine." (PMID 36272975, 2022).